IL6 (interleukin 6)
Diseases named in the same sentence as IL6 in open-access papers (continued):
Sharing a sentence is not in itself a finding about the gene and the disease.
tumor (continued). "Treatment with 5-FU and probiotics reduced the protein levels of anti-inflammatory IL-10 and noticeably increased the protein levels of proinflammatory IL-6 and TNF-α in tumor tissues." (PMID 39062024, 2024). "TAMs can secrete a variety of cytokines, including IL-6, TGF-β and IL-8; induce EMT in tumor cells; and promote tumor metastasis." (PMID 39169402, 2024). "Platycodin D, a major component of Platycodon grandiflorum roots and a component of GJS, significantly inhibits tumor growth by increasing interferon-γ, TNF-α, IL-6, and IL-2 levels and improves immune function." (PMID 39273195, 2024). "Conversely, osteoblasts respond to this stimulation by secreting IGF-1, IL-6, IL-8, FGFs, and TGF-β, all of which are able to stimulate tumor growth." (PMID 39596154, 2024). "Subsequently, the deficiency of miR-338-5p in hypoxic cancer cells moderated the decrease in IL-6 expression and reactivated the anti-apoptotic STAT3/Bcl2 signaling pathway, thus impeding tumor cell death and improving the drug resistance of tumor cells." (PMID 37588219, 2024). "We posit that the ERO1α/IL-6/STAT3/SLC7A11 pathway is critical for mTORC1-mediated ferroptosis resistance and tumor growth and that it can be targeted for the treatment of cancers associated with dysregulated mTORC1 signaling." (PMID 38610018, 2024). "In HCC, SASP components, including IL‐6, IL‐8, CXCL10 and AREG, foster angiogenesis, while overexpression of DNASE1L3 inhibits tumour angiogenesis by disrupting the SASP in response to DNA damage stress." (PMID 39270064, 2024). "For instance, IL-6 and HGF released from adipose stem cells in vWAT promote CRC expansion; in turn, tumor cells produce more neutrophils, NGF, and NT-3, and further recruit more adipose stem cells." (PMID 39125923, 2024). "Conversely, cGAS–STING-dependent activation of NC-NF-κB signaling can drive IL6/STAT3 signaling and EMT programs, which promote tumor growth and metastasis, respectively." (PMID 39295867, 2024). "Activation of this pathway triggers the secretion of IL-6 by TAMs, which then enhances the levels of eukaryotic initiation factor 4A3 (EIF4A3) and the chemokine CCL2 in tumor cells." (PMID 39286635, 2024). "Among these, IL-1B, IL-6, TNF, CXCLs, TGFB1, HMGB1, STAT3, and STAT5 have been reported to contribute to tumor formation." (PMID 39156107, 2024). "Upregulated IL-6 and NF-κB prevent STAT1 and ASK-JNK-mediated cell death, leading to tumor cell survival." (PMID 39464890, 2024). "After THC treatment, a decrease was observed in the level of six cytokines in serum samples, including IL-6 and TNF-α, as well as chemokine (C-C motif) ligand 2 (CCL2), known for its unfavorable effects on tumor prognosis, and reviewed elsewhere." (PMID 38799159, 2024). "We further validated that the representative core genes in the IL-6/JAK/STAT3 pathway (Il6st (Gp130), Fas and Stat1) and the late response of estrogen (St6gal, Areg and Serpina3) were highly reduced in shMCT-1 tumor when compared to scramble tumor." (PMID 38505617, 2024). "Finally, other CAF subpopulations where identified in other tumor types, such as vascular CAFs (vCAFs), found in breast cancer, and cholangiocarcinoma, which highly expressed microvasculature-associated genes (e.g., CD146), as well as inflammatory chemokines such as CCL8 and IL-6." (PMID 38540204, 2024). "Evidence for the role of IL6 and its cognate receptor (IL6R) within the tumour itself and surrounding microenvironment remains a key area of research." (PMID 39766336, 2024). "Our analysis also revealed an enrichment of IL-6/JAK/STAT3 signaling in CD8+ T cells, which is known to enhance proliferation, survival, invasiveness, and metastasis of tumor cells." (PMID 38169544, 2024). "Elevated stress hormones further promote the release of pro-inflammatory cytokines, such as IL-6 and TNF-α, which enhance tumor proliferation and migration." (PMID 39766169, 2024).
tumor (continued). "The IL‐6/STAT3 pathway involves key proteins like Bcl‐2 and Bax, crucial for tumour cell apoptosis and Cyclin D1 and CDK‐4, which contribute to tumour cell proliferation." (PMID 39495702, 2024). "The most studied signaling molecules involved in MSC tumor-tropism are tumour necrosis factor-α (TNF-α), interleukin (IL)-6, and stromal cell-derived factor-1 (SDF-1)." (PMID 38169524, 2024). "Following IL-6-NIS-MSC administration, 131I treatment dramatically slowed tumor development as measured by MRI and increased the median survival of GBM-bearing mice to 60% as compared to controls." (PMID 39199662, 2024). "Additionally, CD109’s interaction with EGFR could amplify pro-inflammatory cytokine production, such as IL-6 and IL-8, by activating downstream pathways like Akt/mTOR and NF-κB, thereby enhancing tumor growth, immune suppression, and potentially contributing to chemoresistance." (PMID 39990858, 2024). "These pro-inflammatory M1-like macrophages are responsible for phagocytosis of cancer cells, antigen presentation and release of cytokines (e.g., IL-6) to recruit natural killer and CD8+ T cells essential for tumor control." (PMID 38504975, 2024). "Chen Z showed that the tumor micro-environment was considerably improved with the concentration of FIB, tissue factor, VEGF, and IL-6 decline after administration of HSOS." (PMID 38555532, 2024). "M1 inhibits tumor growth through the synthesis of proinflammatory cytokines, such as tumor necrosis factor-α (TNF-α), IL-1, IL6, IL-12, IL-23, and reactive nitrogen and intermediate oxygen compounds, thus ensuring the phagocytosis of defective cells." (PMID 39201801, 2024). "Studies have shown that tumour-derived exosomal HSP72 stimulates the expansion of MDSCs through Erk and activates STAT3 by inducing autocrine IL-6 in a TLR2/MyD88-dependent manner." (PMID 38302430, 2024). "Pro-tumour cytokines such as vascular-endothelial growth factor α (VEGF-α) and the interleukins (IL) IL-4, IL-5, IL-6, IL-10, and IL-13 produced by T-helper (Th2) lymphocytes have also been linked to the pathogenesis of MCD." (PMID 40729293, 2024). "MDSCs secrete IL-6 by activating the signal transducer and activator of transcription 3 (STAT3) signaling pathway, promoting tumor growth and invasion." (PMID 38523646, 2024). "IL1B was highly expressed in adrenocortical and medullary tumor samples obtained from the ACME HS and nuclei datasets, while IL6 was highly expressed in all tissues compared with the PitNET datasets obtained by the enzymatic digestion method." (PMID 39839668, 2024). "Conversely, blocking the IL-6/STAT3 signaling pathway hinders CD44 expression as well as the acquisition of CSC-like characteristics and aggressive tumor behavior." (PMID 39092186, 2024). "CpG-ODN-stimulated pDCs have been shown to promote Th17 differentiation through increased secretion of cytokines like IL-6, IL-23 and TGF-β), which can induce tumor regression in mice." (PMID 36798234, 2024). "Tumor cells can release large amounts of pro-inflammatory cytokines, including TNF-α, IL-6, and IL-1β, into the bloodstream." (PMID 39697630, 2024). "IL-6 has been shown to increase the expression of ICAM-1 and VCAM-1 on mesothelial cells, thereby promoting adhesion of tumor cells." (PMID 38689325, 2024). "In summary, high expression of OASL in tumor tissues activates immune responses such as IFN-γ, STAT1, IL6_JAK_STAT3 signaling, which in turn promotes the expression of PD-L1." (PMID 39286258, 2024). "At the same time, lncRNA TSLNC8 inhibited the IL-6/STAT3 signaling pathway, inducing tumor suppression." (PMID 39682098, 2024). "Neovascularization in GBM, essential for tumor growth, depends on several NF-κB target genes, including VEGF, IL-6, and IL-8." (PMID 39684484, 2024). "CAF activation is induced by factors like ECM rigidity, metabolic stress, and signaling molecules such as TGF-β, IL-1, IL-6, and TNF released by both tumor cells and infiltrating immune cells." (PMID 39524442, 2024).
tumor (continued). "IL-6 plays a multifaceted role in the development and progression of PDAC as it can act directly on tumor cells but also modulate the tumor microenvironment." (PMID 39273323, 2024). "In Gprc5a-ko mice, overexpression of IL-6 reprogrammed the STAT3 pathway and induced recruitment of PMN-MDSCs and polarized macrophages to evade host immunity, leading to metastasis of tumor cells within the mouse lung." (PMID 38609997, 2024). "Together, these findings suggest that regulatory T cells infiltrate glioblastoma tumors, promoting the TGF beta, TNF via NF-kB, and IL6/JAK/STAT3 signaling pathways and thereby increasing mesenchymal transition of tumor cells." (PMID 38981682, 2024). "In particular, pro-inflammatory cytokines such as IL-6, IL-1, TNF-α, CCL3 and CCL8 attract innate immune cells to the vicinity of the tumor site." (PMID 38811984, 2024). "Yogurt restored the organ development and promoted the cytokine secretion of IL-6 and IFN-γ in tumor-bearing mice treated with CTX." (PMID 38732641, 2024). "As expected, the proportion of matured and activated DC cells in tumor cells of mice treated with SN38-NPs or SN38-URNPs was increased significantly, and this was accompanied by elevated levels of IFN-γ, IL-6, and TNF-α in the serum." (PMID 38571953, 2024). "In summary, we demonstrate a connection between TGF-β, IL-6, TLR-2 and TLR-4 expression by the primary CRC tumor to SPP1 and FN1 expression in the metastatic intrahepatic tumor." (PMID 39372792, 2024). "Tumor cells can secrete numerous pro-inflammatory factors such as TNF-α, interferon-gamma (IFN-γ), IL-1 and IL-6, and parathyroid hormone-related protein (PTHrP) that can trigger cancer cachexia." (PMID 39697630, 2024). "TCR-engineered CD8+ T cells secreted IL-2, IL-4, IL-6, and IL-10 when cocultured with KRASG12V tumor cell lines." (PMID 39287991, 2024). "We also found that B-ISG15 was enriched in the IL2 STAT5 signaling and IL6 JAK STAT3 signaling gene sets, and IL-6/JAK/STAT3 signaling drives tumor cell proliferation, survival, invasion, and metastasis while inhibiting the antitumor immune response." (PMID 38216927, 2024). "Meanwhile, IL-17F was shown to directly inhibit the vascular endothelial cells and decrease the expression of angiogenesis factors including IL-6, IL-8, and VEGF, thus inhibiting tumor angiogenesis and tumor growth." (PMID 39906741, 2024). "This investigation confirms our earlier observation of the importance of IL-6/STAT signalling in the communication between cells in the OPSCC TME, an effect which is limited to HPV-negative tumour cells in culture." (PMID 38803348, 2024). "It upregulates cytokines like IL-6 and TNF-α and downregulates miRNA18a via the TLR-4/MYD88 pathway, further supporting tumor growth and immune evasion." (PMID 39273009, 2024). "At the study evaluation timepoint of 2 h post H-FIRE, we observed differential gene expression changes in the genes IDO1, IL6, TNF, CD209, and FOXP3 in treated tumor regions relative to paired untreated tumor regions." (PMID 39335552, 2024). "Silencing FoxO3 in Foxp3GFP−creRorcfl/fl mice accelerates tumor development, accompanied by increased IL-6 and STAT3 expression within the tumor tissue." (PMID 38317142, 2024). "MAPK and IL-6-mediated signaling pathways impact immature MDSCs (i-MDSCs) in the TME, which are activated by IL-6 and attracted to tumor locations where they develop into mature MDSCs and decrease tumor immunity." (PMID 39372416, 2024). "The lAPR and the IL‐1β, IL‐6, and COX‐2 induction can be considered as part of a self‐defensive reaction of tumor cells due to mEHT‐induced stress, although the role of the inflammation in cancer is not fully understood." (PMID 38217262, 2024). "DCs, crucial for the initiation and maintenance of immune responses, are influenced by various factors secreted by tumor cells, including VEGF, IL-6, and IL-10." (PMID 39227970, 2024).
tumor (continued). "Since the cytokines (Cxcl1 and Csf3) involved in immune cell recruitment and survival and Cd84 are elevated at day 7 in tumor-bearing mice, we tested if Ly6G+ mononuclear cells are present in MHV68-infected mice and are also a source of IL-6." (PMID 39338937, 2024). "The IL6–JAK–STAT3 signaling pathway plays diverse roles in tumorigenesis, including angiogenesis, tumor invasion, and migration." (PMID 37261105, 2023). "Expansion and activation of MDSCs in the TME are also dependent on cytokines secreted by tumor cells, such as interferon (IFN)-γ, IL-1β, IL-4, and IL-6 or activated immune cells like GM-CS, G-CSF, and VEGF." (PMID 37410164, 2023). "Phenotype M1 is able to directly kill tumor cells by producing nitric oxide and reactive oxygen species, or by secreting pro-inflammatory cytokines such as tumor necrosis factor-α (TNF-α), IL-6, and IFN-γ." (PMID 37513975, 2023). "They act on targets such as IL-6, FOS, STAT3, ERBB2, and EGF, exerting effects on delaying tumor cell resistance and inhibiting tumor cell invasion and metastasis." (PMID 37990309, 2023). "The process of tumor-related angiogenesis is regulated by various pro-angiogenic factors, such as VEGF and interleukin 6 (IL-6), which are the dominant regulators of the proliferation of endothelial cells and the formation of new blood vessels." (PMID 37691121, 2023). "Inflammatory cytokines (IL-8, IL-6, and so on) in the TME can induce M2 polarization of neutrophil cells and synergistically exert pro-tumor functions." (PMID 37063892, 2023). "In vivo investigation indicated that donepezil inhibits CMF associated cognitive deficiency in mammary carcinoma model by reverting the increased level of proinflammatory cytokines (IL-6 and IL-1β) in CMF treated animal tumor model." (PMID 37631080, 2023). "Specific factors produced by activated T cells, tumor, and tumor stromal cells, such as VEGF, CSF, IL-6, IL-10, MMP-9, TGF-β, NF-kB, and other immune-suppressive mediators, can stimulate the proliferation and activation of MDSCs." (PMID 37857728, 2023). "A study by Panni has shown that M-MDSCs play a significant role in promoting tumor stemness and EMT by regulating the STAT3 pathway through the secretion of IL-6, and MDSCs also induce angiogenesis in a STAT3-dependent manner." (PMID 37857728, 2023). "CSCs also promote the production of IL-6 and IL-1β to mediate Th17 cell differentiation, as well as IL-8 and TNF-α to stimulate neutrophil tumor infiltration and angiogenesis." (PMID 36993986, 2023). "Macrophages in the tumor microenvironment regulate inflammation and adaptive immunity by producing growth factors (e.g., TGF-β1) and cytokines (e.g., TNF-α and IL-6), thereby enhancing angiogenesis." (PMID 36874003, 2023). "The overexpression of miRNA-101 or enriched exosome uptake by macrophages suppresses IL1A and IL6 expression by targeting CDK8, whereas injecting miR-101 into xenografted tumors reduced growth and macrophage tumor infiltration in vivo." (PMID 38002256, 2023). "Encouraged by the data obtained in HNSCC, indicating a central role of FGFR-mediated autophagy in enhancing the release of tumor-promoting factors by stromal cells, we finally aimed to assess if the increase of autophagy observed in #2AK cultures could result in an increased secretion of IL-6." (PMID 36979155, 2023). "MDSCs can also produce IL-6 and TNF-ɑ, which are involved in the IL-6/STAT3 pathway signaling, playing an immunosuppressive role in the tumor microenvironment." (PMID 36593497, 2023). "Here, we show that SC144, a gp130 inhibitor that blocks the IL-6/gp130/STAT3 pathway, induces ICD of tumor cells and polarizes macrophages to M1-phenotype in vitro." (PMID 37553327, 2023). "The differentiation of Th17 cells is increased through the expression of HIF-1α by IL-6 and TGF-β collaboratively and they can promote tumor growth through angiogenic and immunosuppressive effector functions." (PMID 37501379, 2023).
tumor (continued). "In the tumor microenvironment (TME), the IL6/JAK/STAT3 signaling pathway promotes the proliferative, survival, invasive, and metastatic activities of cancer cells, and strongly inhibits the anticancer immune response." (PMID 37651362, 2023). "Inflammatory CAFs with low expression of a-SMA and high expression of IL-6 promote tumor growth, while myofibroblastic CAFs with high expression of a-SMA inhibit tumor growth." (PMID 37064113, 2023). "IL6-activated STAT3 acts on the promoter of the B7-H4 gene and enhances the expression of B7-H4 on TAMs, which is an essential pro-tumor step of blocking effective T-cell immune responses." (PMID 37012233, 2023). "Increases in pro-inflammatory (TNFα, IL-6, and MHC-II) and decreases in pro-tumor (VEGF, CCL2, and CD206) markers in WT tumor-educated BMDMs treated with 100 nM CDDO-Me suggest beneficial polarization of macrophages in vitro." (PMID 36670978, 2023). "Tumor-derived GM-CSF, IL-6, IL-1β, TGF-β, IL-13, IFN-γ, CXCL5 have also been found to regulate MDSC accumulation and the polarization of tumor-infiltrating granulocytic MDSC (G-MDSC) toward an immunosuppressive phenotype." (PMID 38304256, 2023). "The triggering of IL-1/IL-6 axis contributes to CAC development while blocking IL-1β activity demonstrates a substantial decrease in both mucosal damage and tumor development." (PMID 38068869, 2023). "A study has shown that the overexpression of IL‐6 in transgenic mice induces hypervascularization of the cerebellum and enhances the production of vascular endothelial growth factor (VEGF) by tumor cells." (PMID 38023706, 2023). "It has also been reported that macrophages can regulate the tumor microenvironment via producing iNOS, NO, or other pro-inflammatory cytokines (e.g., TNF-α and IL-6)." (PMID 36827169, 2023). "At the cellular level, IL-1β is known to stimulate angiogenesis in the tumor microenvironment (TME), and to induce the production of IL-6 and IL-17A, which are well-established mediators of tumor growth." (PMID 36670473, 2023). "In combination, these data reinforce the correlation of IL-6 and the adenosine pathway in advanced NSCLC and the use of high CRP as a surrogate for an immunosuppressive TIME (tumor immune microenvironment)." (PMID 37852738, 2023). "In these studies, blockade of IL-6 and PD-L1 in murine PDAC models significantly inhibited tumor growth while promoting effector CD8+ T cell infiltration of tumors." (PMID 36881480, 2023). "OLT1177 disrupts IL-1β/IL-6/STAT3 axis in TME resulting in reduced tumor growth through attenuating immunosuppressive activities in MDSCs, and the anti-tumor effect is further enhanced in combination with anti-PD-1." (PMID 36932407, 2023). "The expression levels of monocyte chemokines (csf-1 and ccl-2) in tumor cells of mice treated with EGCG were lower, and the cytokine was skewed from M2-to M1, which was manifested as the decrease of IL-6 and TGF-β, and the increase of TNF-α." (PMID 37560476, 2023). "In this model, tumor microenvironment cells in turn secrete soluble mediators, such as IL-6, TNF-α and VEGF to promote tumor growth." (PMID 37213270, 2023). "By inducing cells to secrete IL-6, substance P, and other cytokines, P2X7 is involved in cell proliferation and tumor metastasis." (PMID 38273855, 2023). "Neovascularization in GBM is critical for supporting the growing tumour, and stimulation of this process is dependent on several NF-κB target genes, including VEGF, IL-6, and IL-8." (PMID 36675073, 2023). "The pro-inflammatory cytokines IL-1β, IL-6, and TNF-α are involved in tumor cell proliferation, angiogenesis, and metastasis and seem to strengthen each other’s mode of action, these being stimulated by the same mediators." (PMID 38137862, 2023). "IL-6 has been reported to induce the expression of HDAC6, concomitantly with increased proliferation, migration, and EMT of tumor cells." (PMID 38258065, 2023).